CXCR2 (C-X-C motif chemokine receptor 2)
Diseases named in the same sentence as CXCR2 in open-access papers (continued):
Sharing a sentence is not in itself a finding about the gene and the disease.
tumor (continued). "In fact, a more glycolytic neutrophil (ckit-CXCR2+ phenotype) is unable to induce T cell death and inhibit interferon-γ (IFN-γ) production by T-cells, thereby enhancing anti-tumor immunity." (PMID 38259490, 2023). "CXCR1 and CXCR2 have comparable affinity to CXCL6 and CXCL8 (IL-8), and CXCR2 mediates tumor angiogenesis." (PMID 37626511, 2023). "Combined inhibition of CXCR2 and CSF1R can reduce granulocyte intratumor infiltration and exhibit strong anti-tumor efficacy." (PMID 37784082, 2023). "Mechanistically, MIF independently interacts with CD74 in a hetero-complex with CD44, CXCR2, CXCR4, and ACKR3 to initiate downstream MAPK and PI3K pathways, all of which influence tumor initiation, growth, and metastatic dissemination." (PMID 38065972, 2023). "provided evidence showing a lower frequency of NK cells in tumor samples of PDAC patients, which was due to downregulated expression of CXCR2, a receptor of several chemokines important for NK cell recruiting." (PMID 37771596, 2023). "Along this line, it has been shown that T-cells engineered with the chemokine receptor CXCR2, binding to the ligand CXCL1 on melanoma cells, had an effective trafficking effect to the tumor site." (PMID 36717905, 2023). "In pancreatic cancer, TAM-derived C-X-C motif chemokine ligand 3 (CXCL3) targets CAFs’ C-X-C motif chemokine receptor 2 (CCR2) to mediate CAF-myofibroblasts (myCAF) transition, subsequent type III collagen generation and tumor metastasis." (PMID 36906534, 2023). "The tumor microenvironment (TME) can secrete CXC chemokine ligands, attracting neutrophils, which possess high levels of chemokine receptors CXCR1 and CXCR2, to the site of the tumor, in a process called chemotaxis." (PMID 37261342, 2023). "CXCR2 is a GPCR for CXC chemokines, CXCL1-3, and CXCL5-8, and is involved in inflammation, angiogenesis, tumorigenesis, and metastasis through tumor-stroma interaction." (PMID 36986488, 2023). "Tumor-produced chemokines, acting through CXCR1 and CXCR2 chemokine receptors, can induce NETosis and aid immune evasion of cancers by physically coating tumor cells and preventing contact with CD8 and NK cells." (PMID 37143649, 2023). "Two subsets of MDSCs expressing different MIF receptors were described: a monocytic MDSC, expressing high levels of CD74, with a large presence within the tumor microenvironment, and a granulocytic MDSC, expressing CXCR2, with a low presence in the tumor." (PMID 36672343, 2023). "We treated the RM-9 tumor-bearing mice with CXCR2 antagonist AZD5069 before and after radiation and monitored the tumor sizes." (PMID 38067390, 2023). "CXC motif chemokine ligand 2 (CXCL2) released by tumor cells, which in turn activates CXC chemokine receptor 2 (CXCR2), and IL-6, IL-8, and IL-1β recruit tumor-infiltrating MDSCs inducing epithelial–mesenchymal transition (EMT) and metastasis." (PMID 36831498, 2023). "After treatment with CXCR2 inhibitor AZD5069, neutrophil infiltration in brain metastases of TNBC is significantly reduced and, thus, tumor metastasis is significantly inhibited." (PMID 37496019, 2023). "Cellular responses, such as tumour cell survival and proliferation, are the consequences of CXCR1 and CXCR2 mediated activation of (PI3K)/Akt and MAPK signalling pathways." (PMID 37170733, 2023). "The blockade of CXCR2 impaired MDSC migration and activation, thereby leading to tumor growth inhibition." (PMID 37895882, 2023). "As an example, C-X-C motif chemokine ligand 5 (CXCL5) is a tumor-secreted chemokine that draws MDSCs expressing C-X-C motif chemokine receptor 2 (CXCR2) and, in consequence, its suppression disrupts tumor development." (PMID 36260158, 2023). "The diagnostic sensitivity of CXCL8 was higher than the well-known tumor marker, CEA, and higher than the specific receptor for CXCL8 (CXCR2)." (PMID 37240178, 2023). "By adding a CXCR2 inhibitor to the dual ICI, impressive tumor control and longer OS were observed in the majority of preclinical models." (PMID 37895882, 2023).
tumor (continued). "This neovascularization is essential to supply nutrients and oxygen to the tumor cells and is probably mainly mediated by interaction of CXCL8 with CXCR2-expressing endothelial cells." (PMID 36725964, 2023). "CXCR2 in NSCLC has been studied mainly in stromal cells and was known to increase tumor inflammation and angiogenesis." (PMID 36611170, 2023). "Endothelial-derived CXCL5 and its receptor CXCR2 promote the migration and intravasation of RCC toward endothelial cells suggesting that crosstalk between endothelial cells and tumor cells has a direct guiding role in driving the metastatic spread of RCC." (PMID 37015905, 2023). "CXCL8 mainly functions through its interactions with CXCR1 and CXCR2, and CXCL8/CXCR1 contributes to the proliferation of tumor cells." (PMID 36647133, 2023). "Human PDAC tumors overexpress CXCR2, and its activation by certain CXC chemokines has tumor- and inflammation-promoting consequences." (PMID 35740692, 2022). "CXCR2, as the putative receptor for ELR+ CXC chemokine-induced angiogenic activity, is widely expressed in tumor cells and stroma cells such as endothelial cells and leukocytes." (PMID 35898871, 2022). "CXCR2 acts as receptor for the chemokines CXCL1–3, 5–8, and its stimulation activates several signaling pathways beneath NFκB, which are involved in tumor cell survival and proliferation." (PMID 35530351, 2022). "PADI4 upregulates the expression levels of KRT14, CXCR2 and TNF-α, which are related to cell proliferation, cell migration, tumour angiogenesis, and tumour immune microenvironment." (PMID 35045833, 2022). "Similar to CXCL1, CXCR2 inhibition decreases the CXCL2-induced neovascularization and tumor progression." (PMID 35954156, 2022). "Inhibition of CXCR2 using small molecule antagonist AZD5069 reversed this behavior, limiting the neutrophil responses to the BrM and retarding the reciprocal tumor development." (PMID 35158784, 2022). "In CRC, macrophages stimulate the primary tumor to produce CXCL1, a member of CXC chemokines, binding to CXCR2 together with CXCL2, CXCL5, and CXCL8." (PMID 35879739, 2022). "Myeloid-cells tumor homing is largely regulated by multiple ligand-receptor interactions, mainly the colony-stimulating factor-1 (CSF1R), the C-X-C Motif Chemokine Receptor 2 (CXCR2), the C-C chemokine receptor type 2 (CCR2) and type 5 (CCR5)." (PMID 36077813, 2022). "In 2011, Varney found that after applying CXCL8 receptor CXCR2 antagonist to CRC-bearing nude mice, tumor angiogenesis was significantly inhibited, and liver metastasis of CRC was also significantly inhibited." (PMID 35845924, 2022). "Therefore, a consequence of AR-targeted therapy-induced hypoxia may be to increase CXCR2 expression in tumor cells, which by extension results in the selection of cells undergoing transition to neuroendocrine prostate cancer, a known driver of castration-resistance." (PMID 35302608, 2022). "IL4 signaling in macrophages upregulates the expression of the chemokine receptor CXCR2, necessary for IL4-mediated tumor cell extravasation in vitro." (PMID 36077870, 2022). "A variety of chemokine/chemokine receptor strategies have been utilised in immunotherapeutic T cell preclinical work to facilitate CAR T cell targeting to tumour masses, including the exploiting the CXCR3, CXCR2, CCR5, CCR2, and CCR3 axes." (PMID 35205725, 2022). "In HCC, CXCR2-expressing CAR-T cells significantly accelerate trafficking and accumulation in tumor, and exhibit improved anti-tumor efficacy." (PMID 36093115, 2022). "It was also reported that the treatment with a small-molecule inhibitor of CXCR2 and CXCR1, SX-682 (SX), sensitized tumor-bearing mice to the anti-PD1 antibody." (PMID 35664746, 2022). "Given that tumor-derived CXCL5 promotes tumor cell EMT and MDSC recruitment by activating CXCR2, we proposed that HSC-derived FAPα promoted tumor cell EMT and MDSC recruitment through the CXCL5/CXCR2 axis." (PMID 35951441, 2022).
tumor (continued). "In pre-clinical models, CXCR2 inhibition showed reduced MDSC frequency, increased T-cell infiltration, decreased tumor progression, as well as improved response to anti-PD-1 treatment." (PMID 35158779, 2022). "IL4 signaling in macrophages controlled the expression of the chemokine receptor CXCR2, necessary for IL4-mediated tumor cell extravasation in vitro." (PMID 36077870, 2022). "Studies investigated that CXCL1/CXCR2 and CCL26/CX3CR1 axis are two important pathways that induce the homing of MDSCs to the HCC microenvironment, thereby promoting immune escape and tumor growth." (PMID 36093115, 2022). "CXCR2 and its ligands were described as having an antimetastatic role in renal cell carcinoma where CXCL5 and CXCL8 produced by tumor cells can attract neutrophils with antitumor activity." (PMID 35158948, 2022). "By binding to CXCR1 and CXCR2, CXCL7 can affect tumor proliferation, invasion, migration, and tumor angiogenesis in an autocrine and paracrine manner through multiple signaling pathways." (PMID 35837284, 2022). "In mice, knockout of CXCR2, the primary neutrophil chemotaxis receptor, inhibits TAN infiltration into tumors, leading to T cell-dependent tumor growth inhibition." (PMID 36077755, 2022). "In detail, genetic modification of CAR-Ts for the expression of IL-8 receptors (CXCR1 or CXCR2) and the utilization of the tumor-secreted IL-8 to usher the IL-8 receptor-modified CAR-Ts (IL-8R-CAR-Ts) to the tumor foci results in enhanced antitumor activity." (PMID 35634281, 2022). "The anti-tumor effects of blocking the CCL2/CCR2 and CXCLs/CXCR2 axes by CCR2 and CXCR2 antagonists in combination with TACE were evaluated in HCC rats." (PMID 36403057, 2022). "Like CXCR2 inhibition, targeting CXCR4 represents a different strategy to reduce tumor recruitment and neutrophil mobilization from the BM." (PMID 35664746, 2022). "Compared to the control group, the number of tumors and the maximum tumor volume were reduced following intraperitoneal injection of CCR2 and CXCR2 antagonists for 6 weeks." (PMID 36403057, 2022). "Bone-homing tumor cells tend to overexpress chemokine receptors, CXCR4, CXCR6, and CXCR2 that subsequently contribute to the movement of the tumor cells from the bone marrow to other organs by seeking CXCL12, CXCL-16, and CXCL-10 respectively." (PMID 35399952, 2022). "In papillary thyroid carcinoma cells, the CXCL5/CXCR2 axis was found to enhance mesenchymal marker vimentin and snail expression, thus promoting EMT of the tumor cells." (PMID 36612163, 2022). "Evidence suggests that tumor cells promote the release of NETs from neutrophils through stimulation, such as secretion of IL-8/CXCL8 and CXCR1/CXCR2 agonists, which provides an explanation for the link between NETs and cancer." (PMID 36341351, 2022). "In previous studies, CXCL8 (IL-8), as a major pro-inflammatory chemokine, mediates tumor immune escape through extracellular binding of two G-protein-coupled receptors (CXCR1 and CXCR2)." (PMID 36532065, 2022). "Stimulation of CXCR2 on cancer cells converts them into tumor-initiating CSC responsible for invasive behaviors and paradoxically enhanced tumor aggression after therapy." (PMID 35628979, 2022). "Combined with chemokine receptor 2 (CXCR2), CXCL5 participated in recruiting leukocytes, proliferating tumor cells, and metastasis." (PMID 35150082, 2022). "Expression profiles of MIF, CXCL12, and the receptors CXCR4, CXCR2, CXCR7, CD74, and CD44 were first analyzed using an RNA sequencing (RNA-seq) dataset (GSE62564) of 498 primary NB tumor samples." (PMID 35715791, 2022). "It is reported that the chemokine receptor CXCR2 and their ligands CXCL1-3 and CXCL5-8 are in charge to attract neutrophils to the tumor and develop an inflammatory response." (PMID 36226048, 2022). "IL4 signaling in macrophages controlled the expression of CXCR2, which is necessary for IL4-mediated tumor cell extravasation in vitro." (PMID 36077870, 2022).
tumor (continued). "CXCR2 is a G-protein-coupled receptor that regulates neutrophil and MDSC migration in the TME of PC, which drives tumor invasion and metastasis." (PMID 35139879, 2022). "First, in vivo tests have shown that blocking CXCL5 or applying CXCR2 antagonists can slow disease progression by blocking the AKT/NF‐κB signaling pathway, thereby effectively reducing the blood supply to the tumor." (PMID 35702353, 2022). "CXCL2 is highly expressed in HCC, and engineered overexpression of the CXCR2L receptor (CXCR2) on GPC3-CAR-T cells was shown to enhance CAR-T infiltration and expansion at the tumour site in a xenogeneic HCC model." (PMID 35158772, 2022). "Activation of CXCR2 inversed inactivation of AKT/ERK signal pathways and the tumor-suppressive effects induced by PDCD10 silencing." (PMID 35963638, 2022). "MIF is highly expressed in head-and-neck cancer (HNC) and stimulates functions of neutrophils by enhancing their CXCR2-dependent recruitment and survival and release of CCL4 and MMP9, in turn, promoting tumor progression." (PMID 35842634, 2022). "Taken together, our results show that FAPα induces CXCL5 secretion in HSCs to promote tumor cell EMT and MDSC recruitment through activation of CXCR2, thus facilitating vessel co-option." (PMID 35951441, 2022). "Second, we pharmacologically blocked myeloid cell migration into the tumor using a combination of CCR2 (BMS CCR2) and CXCR2 (SB225002) chemokine antagonists." (PMID 36104342, 2022). "Tumor cells can adhere to and activate platelets and recruit neutrophils through the CXCL5/CXCL7/CXCR2 axis to promote the formation of early metastatic niches." (PMID 35837284, 2022). "Other studies have demonstrated that CSF-1R blockades combined with CXCR2 antagonists, ICB or anti-VEGFR mAbs have better efficacy in tumor patients." (PMID 36246629, 2022). "In both tumor and normal lung tissue of all core atlas samples, the neutrophil cluster (FCGR3B, CSF3R, CXCR2, and G0S2) comprised 8,468 cells with overt low mRNA counts." (PMID 36368318, 2022). "Our results showed that the expression of CXCR2 and CD101 in peripheral blood G-MDSCs of tumor-bearing mice was reduced." (PMID 35013108, 2022). "Depletion of CXCR2+ TANs attenuate PDAC metastasis, promotes T cell entry, and sensitizes tumor cells to PD-1 blockade in mice." (PMID 36230914, 2022). "As X-rays induced IL-8 cytokine secretion from tumor cells, CAR T cells expressing CXCR2, which is a receptor for IL-8, migrated to tumor lesions irradiated by X-ray, leading to enhanced antitumor effects." (PMID 34209505, 2021). "We crossed Cxcr2 KO mice and PyMT mice (both in a FVB background) and first analyzed the rate of tumor growth in these animals." (PMID 34070438, 2021). "IL-8 and its receptors CXCR1 and CXCR2 are overexpressed in HNSCC and involved in progression, metastasis, and aggressive tumor phenotype." (PMID 33925575, 2021). "CXCL8 promotes tumor angiogenesis by maintaining the proliferation and activity of endothelial cells, and CXCR1 and CXCR2 are the basis of this function." (PMID 33767987, 2021). "Then, we used flow cytometry to label and analyze the number of CCR3+, CCR9+, CCR10+, CXCR2+, CXCR5+, and CXCR6+ cells expressed different isotype antibodies including IgA, IgG, and IgM in the lung metastases of cKO and control tumor-bearing mice." (PMID 33707428, 2021). "As with CXCR2, the CCR2/CCL2 axis is also involved in recruiting myeloid cells to the tumor microenvironment." (PMID 34203869, 2021). "Antagonists of CXCR2 (S-265610) and CXCR4 (AMD3100) altered the recruitment of immature myeloid cells (iMCs) to the tumor and thus reverted the environment that favors tumor progression." (PMID 33968014, 2021). "In human BC PDX, the use of a specific antibody against IL-8 receptor, CXCR-1, or an inhibitory molecule against to CXCR-1 and CXCR-2, repertaxin, favored the eradication of CSC pool, thus impeding tumor progression." (PMID 34354950, 2021).
tumor (continued). "Among the chemokines regulated by USP12 in tumour cells, CXCL1 and CXCL8 share the chemokine receptor CXCR2 and are strong chemoattractants that recruit TAMs and MDSCs38–40." (PMID 34381028, 2021). "In PDAC, the CXCR2 axis is involved in MDSC recruitment, angiogenesis, tumor cell proliferation and migration." (PMID 34359823, 2021). "Here, we reported that MK3 expression was positively correlated with the majority of chemokines and chemokine receptors, such as CCL, CXCL12, CCR, CXCR2, CXCR4, and CX3CR1, which play pro-tumor roles." (PMID 34938665, 2021). "Two independent research groups described that the use of CXCR-2 inhibitors, AZ13381758 and SB225002, suppresses tumor progression and hampers chemotherapy resistance in BC and pancreatic adenocarcinoma, respectively." (PMID 34354950, 2021). "CXCR2 inhibition prevented TAN accumulation in PDA TME, potently suppressed tumor growth and metastasis and sensitized PDA tumors to anti-PD-1 therapy." (PMID 34290984, 2021). "The chemokine receptor CXCR2 and its ligands CXCL1, CXCL2, CXCL3, CXCL5 and CXCL8 play critical roles in the chemoattraction of neutrophils towards tumor tissues." (PMID 34429454, 2021). "Antagonists of CXCR2 (S-265610) and CXCR4 (AMD3100) altered the recruitment of immature myeloid cells to the tumor." (PMID 35008832, 2021). "High CXCR2 and CD11b levels were correlated with elevated density of tumor-infiltrating lymphocytes (TILs), CD8+ cytotoxic lymphocytes, expression of PD-L1 by tumor and stromal cells and of PD-1 by stromal cells." (PMID 34066060, 2021). "Tumor cells use chemokines to attract TANs to the tumor site, such as the potent neutrophil chemoattractant CXCL8, which entrains the CXCR1 and CXCR2 expression on neutrophils." (PMID 33936029, 2021). "The same study further showed that the chemokines binding to CXCR2 (e.g., CXCL1 and CXCL2) were responsible for BM-neutrophils’ extravasation into the circulation and for their further migration into the tumor." (PMID 34680231, 2021). "The presence of tumor cells significantly stimulated the migration of PMN-MDSC, which was completely abrogated when the CXCR2 inhibitor was added to the culture." (PMID 33578808, 2021). "IL8 also upregulated PLAU secretion of tumor cells, which is also reversed by SB225005, a CXCR2 inhibitor." (PMID 33574243, 2021). "Recently, CXCR2-CAR-T cells were generated to target hepatocellular carcinoma, in which the T cell infiltration, as well as anti-tumor effects, were improved." (PMID 34830003, 2021). "Blockage of CXCR2 signaling with SB225002, a CXCR2 antagonist, significantly reduced tumor growth and CXCR2+ VM structures in vivo." (PMID 34203660, 2021). "We assessed the peritoneal tumor burden of OC under lean and obese states by feeding a normal diet (ND) and a high-fat diet (HFD), respectively, in adipocyte-specific CXCR2 cKO and WT mice." (PMID 34638514, 2021). "Higher quantities of CXCR2-positive cells were correlated with elevated density of tumor-infiltrating lymphocytes (TILs), CD8+ cytotoxic lymphocytes, expression of PD-L1 by tumor and stromal cells and of PD-1 by stromal cells." (PMID 34066060, 2021). "In Cxcr2 knockout PKF (LSL-KrasG12D/+; Tgfbr2flox/flox, Ptf1a-Cre) mice, infiltration of myeloperoxidase+ (MPO+) neutrophils and CD11b+Ly6G+ MDSCs to tumor is decreased compared to control animals." (PMID 34439836, 2021). "Our analysis implied that tumor cells co-express CXCL1 and EGFR, but expression levels of CXCR2, HB-EGF, and ADAMs are relatively low." (PMID 33941851, 2021). "The inhibition of CXCR2 expression in MDSCs or YAP silencing in tumor cells inhibits tumor growth, suggesting that YAP-mediated recruitment of MDSCs is required for tumor progression." (PMID 34439395, 2021). "Other receptors such as CCR5, CCR6, CXCR2 and CX3CR1 were mostly identified for their expression and function in immune cells from the tumor microenvironment." (PMID 35008294, 2021).